BMP7 (bone morphogenetic protein 7)
Diseases named in the same sentence as BMP7 in open-access papers (continued):
Sharing a sentence is not in itself a finding about the gene and the disease.
tumor (continued). "When transplanted into the cleared fat‐pad of nude mice, Bmp7‐null 4T1 cancer cells grew ≈60% less than control cells as measured by tumor volume." (PMID 38708713, 2024). "Clinical studies have also found BMP-7 expression in the tumor cell membrane and cytoplasm of non-small cell lung cancer (NSCLC), with high cytoplasmic BMP-7 expression associated with tumor progression and adverse prognosis." (PMID 38571500, 2024). "BMP-7 has been shown to inhibit cell proliferation of G-402 kidney tumor cells and tumor size in vivo." (PMID 38892327, 2024). "This clear-cut view has changed, however, with the recent demonstration by two independent studies of the oncogenic impact of BMPs, and, in particular, of the role of BMP2 and BMP7, on the invasion potential of tumor cells." (PMID 38542334, 2024). "The involvement of BMP7 in the proliferation of tumours, disease progression and worse overall survival is therefore highlighted." (PMID 37688374, 2023). "BMP7 expression was seen in the cytoplasm and nucleus of tumour cells with predominantly granular/diffuse staining." (PMID 37688374, 2023). "BMP7 works differently depending on the cancer type and its interactions with different receptors or molecules within the tumour microenvironment." (PMID 37688374, 2023). "Data, however, is conflicting as there are reports of BMP7's pleiotropic role in suppressing but also promoting tumour development and metastasis." (PMID 37688374, 2023). "For example, most studies suggesting that BMP-7 is linked to adverse outcomes in the context of cancer, base their conclusions on detection of increased BMP-7 levels in tumor tissue." (PMID 37626268, 2023). "Exosomal miR-17-92 clusters from M2-like TAMs were shown to induce a mismatch in the TGF-β1/BMP-7 pathway of HCC tumour cells by modulating post-transcriptional and post-translational modifications of various proteins." (PMID 37894344, 2023). "The homogeneity of BMP7 expression within the tumour section justified the use of tissue microarrays in this study." (PMID 37688374, 2023). "Collectively, aberrant expression of BMP7 and its involvement in tumour metastasis has been suggested but requires further investigation to confirm the nature of its involvement." (PMID 37688374, 2023). "BMP7 protein expression was analysed by immunohistochemistry using tissue microarray and full face tumour sections." (PMID 37688374, 2023). "In the elderly, this intrinsic tumor-suppressor mechanism decreases with the age-related decline in BMP7-secreting NSC." (PMID 35456027, 2022). "BRAFWT tumor cells of the PT region highly expressed BMP7, whose elevated expression was known to be correlated with tumor invasion, metastasis, recurrence, and cancer-related death." (PMID 35974387, 2022). "Using a prostate BM metastasis model Sharma and coworkers found that the expression of osteonectin by tumor cells can up-regulate bone morphogenetic protein 7 secretion by stromal cells leading to quiescence of the tumor cells." (PMID 34838648, 2022). "Consistent with the antifibrotic role of Meflin, enacted by augmenting BMP7 signaling and suppressing Lox activity, the oral administration of Am80 induced changes in collagen configuration, decreased tumor tissue stiffness, and increased tumor vessel area." (PMID 35884375, 2022). "Tumor cells secrete BMP7 and act on macrophages in the tumor microenvironment and impair pro-inflammatory responses." (PMID 36353620, 2022). "In tumor tissue, BMP7 improved the microenvironment through the suppression of extracellular matrix formation." (PMID 35890230, 2022). "For example, BMSCs, one subtype of bone stromal cells, can either promote or impede the progression of tumor dormancy by secreting BMP7, TGFβ2, GAS6." (PMID 34712663, 2021). "In these cancers, BMP7 suppresses tumor growth by reducing the gene expression of tumorigenic factors and by inducing the differentiation of cancer stem cells." (PMID 34680590, 2021).
tumor (continued). "It has been shown that BMP7 not only promoted growth stimulatory but also promoted inhibitory effects in tumor cells, and BMP7 was related to the postoperative prognosis of NSCLC patients." (PMID 34036102, 2021). "We found that BMP7 was overexpressed in the progressed sample (PD) compared with primary tumor (pretreatment)." (PMID 32973129, 2020). "Then we compared the expression of each member in ccRCC tissues and corresponding noncancerous normal tissues, unfortunately we found that BMP4, BMP5, and BMP7 expression was lower in tumor tissues." (PMID 31155610, 2020). "BMP7 (secreted from bone stromal cells) in the microenvironment can simultaneously regulate dormant tumor cells and cancer stem cells." (PMID 32796813, 2020). "Our findings show that BMP7 regulates proinflammatory responses in the tumor microenvironment by suppressing mitogen-activated protein kinase 14 (MAPK14) signaling in macrophages and CD4+ T cells." (PMID 32973129, 2020). "In cancer cells, BMP7 has both oncogenic and tumor suppressor-like functions and is known to antagonize the TGF-β signaling axis." (PMID 32117236, 2020). "We found that BMP7 inhibition via follistatin decreased tumor growth and extended survival compared with anti-PD1 therapy only." (PMID 32973129, 2020). "In conclusion, we demonstrated that secreted BMP7 promotes resistance to anti-PD1 therapy by repressing macrophage-mediated inflammatory responses and Th1-associated cytokines in the tumor microenvironment." (PMID 32973129, 2020). "Immunofluorescence analysis of tumor sections showed a significant BMP7-dependent reduction in CD8+ T cells at both the 2- and 3-week time points (p = 0.012 and p < 0.001, respectively)." (PMID 32117236, 2020). "BMP7 secreted by tumor cells acts on macrophages and CD4+ T cells in the tumor microenvironment, inhibiting MAPK14 expression and impairing pro-inflammatory responses." (PMID 32973129, 2020). "We next investigated if tumor-secreted BMP7 regulates IL1A, IL1B, TNF, and CCL5 via MAPK14 in macrophages." (PMID 32973129, 2020). "Implantation of MDA-231 cells engineered to overexpress BMP7, or injection of recombinant BMP7, however, reduced (by 50%) the number of osteolytic lesions, overall tumor burden and the total osteolytic area." (PMID 29799477, 2018). "Here, we detected significantly lower levels of BMP7 and significantly higher levels of microRNA-137 (miR-137) in the BC specimens, relative to paired adjacent non-tumor breast tissue." (PMID 28407692, 2017). "The levels of BMP7 and miR-137 in 40 pairs of resected BC tissues (Stage IV) and adjacent non-tumor breast tissues (NT) were measured by Western blot and RT-qPCR, respectively." (PMID 28407692, 2017). "Functional studies revealed that miR-342 regulates genes involved with tumor cell death cancer pathways such as GEMIN4 (Gem nuclear organelle associated protein 4) and BMP7 (Bone morphogenetic protein 7)." (PMID 28574440, 2017). "More importantly, BMP7 expressing tumours showed an accelerated BM formation (p = 0.04), which held true for invasive ductal carcinomas (p = 0.033) but not for invasive lobular carcinomas (p = 0.29)." (PMID 28194227, 2017). "Although we began to measure the tumor sizes when the tumors from all the conditions were detectable, we have to point out that 0.05% BMP7 tumors arose later in time than 0.01% BMP7 and control tumors." (PMID 25860932, 2015). "We first confirmed that the tumor cells in vitro maintain the high Bmp7 expression seen in the primary tumors of origin and that they express BMP receptors." (PMID 26337467, 2015). "Data from xenografts confirmed reduced and delayed tumor formation for animals treated with BMP7-loaded microspheres." (PMID 25860932, 2015). "We then studied the possible correlations between BMP7 levels and either clinical parameters of the patients or tumor characteristics." (PMID 26337467, 2015). "We found a net reduction in tumor growth in vivo when cells were exposed to the microspheres releasing BMP7." (PMID 25860932, 2015).
tumor (continued). "Our finding is in agreement with that of others showing that BMP7 release from endogenous neural precursor cells can induce tumor stem cell differentiation and reduce the ability for tumor initiation, therefore, providing a protective action in animals." (PMID 26546412, 2015). "Previous studies have shown that treatment of GBM-TICs with BMP4 or BMP7 triggers Smad-mediated signaling, leading to the inhibition of cell proliferation, the induction of differentiation and a reduction of tumor formation in immunodeficient mice." (PMID 25860932, 2015). "Using an in vitro co-culture endothelial cord formation assay, we investigated the role of a BMP7 variant (BMP7v) in VEGF, bFGF, and tumor-driven angiogenesis." (PMID 25919028, 2015). "The lag time between the subcutaneous transplantation and the appearance of a detectable tumor mass was 40 days for control and 0.01% BMP7 tumors, while 0.05% BMP7 tumors were visible approximately 10 days later." (PMID 25860932, 2015). "In order to test the effect of BMP7 on tumor growth, 1.5 × 106 cells mixed with microspheres (blank, 0.01% BMP7, and 0.05% BMP7 loading) were subcutaneously transplanted into nude mice flanks." (PMID 25860932, 2015). "Using a large cohort of well-characterized PCC/PGL patients, we here confirmed that the BMP7 protein is highly expressed in >70% of tumors; this correlates with extra-adrenal location and tumor size." (PMID 26337467, 2015). "The aim of the present study was to evaluate expression of additional regulators belonging to the stem cell niche, OCT4, SOX2 and BMP7, as well as some microRNAs, reported to act as tumor suppressors or oncomiRs." (PMID 25340937, 2014). "Released BMP7 showed a remarkable capacity to stop tumor formation in an in vitro GIC model and strongly limited growth of GIC orthotopic xenografts in immunocompromised mice (González-Gómez and collaborators, unpublished)." (PMID 24877113, 2014). "The stem cell master regulator SOX2 was increased by NSAIDs (p<0.01), as well as the tumor suppressor miR-630 (p<0.01), while BMP7, a marker for poor prognosis in CRC, was downregulated by NSAID (indomethacin, p<0.02)." (PMID 25340937, 2014). "Out of the 6 initially sensitive patients, 5/6 tumor samples collected after treatment had an increase of BMP7 expression." (PMID 24069261, 2013). "In a mouse model, BMP7 injection significantly limited tumor growth, whereas inhibition of BMP7 increased bone metastasis." (PMID 24502434, 2013). "In TβRII KO tumor epithelium compared with TβRIIfl/fl epithelium, Igfbp4 and Tspan13 expression was upregulated while Col1α2, Bmp7, Gng11, Vcan, Tmeff1, and Dsc2 expression was downregulated." (PMID 22748014, 2012). "The modulation of selected genes such as BMP7, EpCAM and VCAN entailed an increase in the proteins encoded by them, indicating that high CD157 expression alters tumor cell phenotype." (PMID 22916288, 2012). "In opposition, in an in vivo xenograft mouse model of MDA-MB-231 cells, BMP7 reduced tumor growth as well as the formation and growth of bone metastases." (PMID 22118688, 2011). "Bone morphogenetic protein-7 expression was correlated with tumour size, nodal involvement, lymphatic invasion, venous invasion and histology (P<0.05)." (PMID 21224856, 2011). "The effect of BMP-7 on tumor development was examined in a homozygous BALB/C nude mouse tumor xenograft model." (PMID 23675191, 2010). "Prior to examining the effects of BMP-7 on the kidney and lung tumor cell lines, we first established that mRNAs coding for all three type I and one type II receptor were expressed in both tumor cell lines." (PMID 23675191, 2010). "BMP7 methylation was verified in a total of 4 tumour specimens (two PP3, two PP4) as well as two normal samples from separate cases." (PMID 19283074, 2009). "In contrast, BMP7 can promote cell invasion and tumor growth and directs cancer to metastasis or exerts malignant fibrinogenic effects." (PMID 18816401, 2008).
tumor (continued). "Follow-up studies should be pursued to address possible effects of BMP-7 treatment on EndMT in tumours and to identify other EndMT targets." (PMID 18797460, 2008). "On the other hand, BMP-7 may limit the invasion range of the tumor by antagonizing the fibrosis of the TGF-β signal and EMT." (PMID 40696418, 2025). "The elevated level of extracellular BMP-7 suppresses the migration and invasion of tumour cells." (PMID 39941741, 2025). "In the SWI/SNF-mutant cohort, a seven-gene signature comprising CRIM1 (angiogenesis), VEGFC (lymphangiogenesis), BMP7 (tumor microenvironment regulation), NR1D2 (immune modulation), BMPR1B (tumor proliferation), CR2 (B-cell activation), and TAPBPL (antigen presentation) was ultimately retained." (PMID 41438758, 2025). "The sex-divergent effect on tumor size may be related to decreased AR in male mice and/or the observed sex-divergent impact of lead on BMP-7 expression." (PMID 38892327, 2024). "Similarly, using the in vivo transplantation assay, we found that PyMT cells with reduced Bmp7 and Inhba expression had a ≈ 60% reduction in tumor growths." (PMID 38708713, 2024). "Beyond Sema4F, multiple axon-related molecules, classified for their function in tumor axonogenesis, such as Bmp7, Robo1, Fibronectin, or Nrp1, and the synaptic adhesion molecule IGSF11/VSIG-3 are regulated upon TGFβ−mediated EMT induction, hnRNP E1 silencing, or Platr18 overexpression." (PMID 34810279, 2022). "Moreover, BMP7 expression in NSCLC was correlated with the progression of the tumor and poor prognosis." (PMID 34036102, 2021). "Next, we hypothesized that secreted BMP7 negatively affects immune cells in the tumor microenvironment of anti-PD1-resistant tumors." (PMID 32973129, 2020). "Genes and gene subsets identified in this study may function to facilitate tumor immune evasion, as evidenced by confirmatory phenotypic observations associated with RCOR2 and BMP7 expression." (PMID 32117236, 2020). "Moreover, suppression of GATA6 induced expression of the Bmp receptor (Bmpr1b) and rendered these tumor cells more sensitive to exogenous Bmp7 stimulation and downstream Smad9 expression." (PMID 32157212, 2020). "miR-342 acts as a tumor suppressor and can sensitize ER-positive tumors to endocrine therapy by regulating genes involved in cell death pathways, such as gem nuclear organelle associated protein 4 (GEMIN4) and bone morphogenetic protein 7 (BMP7)." (PMID 32967267, 2020). "Interestingly, in non-tumour-bearing mice, Bmp7 expression is substantially higher in the brain than the lungs, whereas the expression of Tgfb1 is higher in the lungs compared with the brain." (PMID 30642388, 2019). "Finally, we demonstrate that either ectopic expression of ID2 or BMP7-induced ID2 expression protects tumour cells from anoikis." (PMID 30642388, 2019). "Inhibition of miRNA-137 rescued BMP7 expression and repressed tumor cell migration." (PMID 29799477, 2018). "BMP7 treatment results in decreased tumor growth both in vitro and in vivo." (PMID 29642534, 2018). "In addition, fibroblast proliferation and mesenchymal cell proliferation were significantly enriched GO terms; the expression levels of TGFβ1, S100A6, PDGFA, and BMP7 were enriched in organoids (and tumor), compared with fetal retina." (PMID 30353124, 2018). "This study is interesting but also suggests that the role of a molecular could be very different from cancer to cancer, since BMP7 is believed to be a tumor suppressor in many cancers." (PMID 28407692, 2017). "Our data demonstrate that telomerase maintenance of telomeres in tumor cells is subject to regulation by extracellular cytokine and that the BMP7 pathway plays a significant role in the negative regulation of telomerase activity and telomere maintenance in cancer." (PMID 27696331, 2017).
tumor (continued). "By analysing primary tumour samples from 483 women with BC (only in 409 protein expression was retrieved), it became clear that tumours expressing BMP7 were more prone to develop BM (20% versus 14%, median follow-up time of 15 years), although this was not a statistically significant difference." (PMID 28194227, 2017). "Thus, our data showed that prolonged exposure to BMP7 induced tumor cell growth arrest, senescence and death." (PMID 27696331, 2017). "By manipulating endogenous Bmp7 levels in PCC cell lines (overexpression and knockdown) and in primary rat tumor cells (knockdown), we could demonstrate that endogenous Bmp7 overexpression promotes oncogenic features in these cells." (PMID 26337467, 2015). "Similarly, bone-derived BMP-7 induced growth-arrest of cancer stem cells which eventually led to tumor dormancy." (PMID 26318423, 2015). "We anticipate that more sustained release profiles and larger BMP7 doses may further prevent tumor growth." (PMID 25860932, 2015). "We also explored whether BMP7 signaling in tumors lead to the differentiation of tumor initiating cells, as suggested by other authors." (PMID 25860932, 2015). "Similarly, bone morphogenetic proteins (BMPs)— BMP2, BMP4, and BMP7, and all-trans RA have been shown to inhibit tumor initiation by promoting astorglial and neuronal differentiation in GBM cells." (PMID 26307681, 2015). "Primary tumors treated with BMP7-loaded microspheres showed delayed tumor growth and lower tumor final volume, which could be correlated with the activation of the BMP canonical pathway." (PMID 25860932, 2015). "At relapse, these BMP7-positive cells may represent the majority of tumor cells and became detectable." (PMID 24069261, 2013). "The role of BMP7 in oncogenic processes was recently investigated in various tumor models." (PMID 24069261, 2013). "Among the upregulated genes, we identified several oncogenes (Ets2, Fyn, Fos, Rab30 and Src), various tumor markers (Cyp1b1, Gpa33, Cd47, Fam129a, st7l, chka, Lgalsbp, Antxr1 and Ly6a) and other genes related to tumor promotion (Cxcl10, Trim25, Grn, Foxc2, Bmp7 and Irs1)." (PMID 23936067, 2013). "One hypothesis in MCL could be that, before therapy, BMP7-positive cells had a proliferation disadvantage compared to BMP7-negative cells that compose the majority of tumor cells, and would be undetectable but present in the MCL." (PMID 24069261, 2013). "BMP7, a tumor network-specific molecule, can act as transcription factor and may as such contribute to upregulation of c-Myb as well as of c-Fos, the latter possibly by other means." (PMID 21464922, 2011). "One of these factors could be BMP-7, which we have previously demonstrated to inhibit tumor growth in animal models of osteolytic bone metastasis." (PMID 21249149, 2011). "In this context, BMP-7 expression may be connected with tumour aggressiveness beyond the specific organ." (PMID 21224856, 2011). "Osteolytic cancer cell-derived noggin may antagonize endogenous, osteoblast-derived BMP-7 and, therefore, allow escape from its inhibitory effect on tumor growth." (PMID 21249149, 2011). "In addition, implantation of the BMP-7-treated A-549 cells into nude mice resulted in ectopic bone formation surrounded by tumor cells." (PMID 23675191, 2010). "The absence of BMP7 mutations in early-onset Hispanic/Latino patients suggests a distinct molecular profile that may influence tumor behavior or response to treatment in this population." (PMID 39682092, 2024). "Moreover, we found that FAK KD HepG2 and Huh-7 cells, but not macroH2A1 KD HepG2 and Huh-7 cells, displayed a simultaneous significant increase (p < 0.01) in the mRNA levels of cancer stemness suppressor genes GATA6, SMAD4, and BMP7, and of tumor-promoting genes KDR and SOX2." (PMID 33182805, 2020). "However, in this model, BMP7 expression synergized with ICB treatment to suppress tumor growth." (PMID 32117236, 2020).